SIRPA (signal regulatory protein alpha)
Diseases named in the same sentence as SIRPA in open-access papers (continued):
Sharing a sentence is not in itself a finding about the gene and the disease.
breast carcinoma (31 papers, 2012 to 2026). "Blocking SIRPα on neutrophils with anti-SIRPα antibodies significantly enhances ADCC mediated by IgA2 variants of cetuximab and trastuzumab against HER2-positive breast cancer cells and EGFR-positive epidermoid carcinoma cells." (PMID 40589735, 2025). "This indicates that SIRPα-Fc has CD47-mediated agonist activities in breast cancer stem cells affecting proliferation and metastasis pathways that differ from those of CC-90002." (PMID 38495618, 2024). "Treatment with SIRPα-Fc significantly increased the formation of mammospheres by breast cancer stem cells as compared to CC-90002 treatment or controls." (PMID 38495618, 2024). "Similar to our previous IHC results for Kaiso, we observed that Kaiso and now SIRPA protein levels increased in AA breast cancer patients." (PMID 37190208, 2023). "Our current analysis of TCGA data and PANCAN_RPPA data and from breast cancer patients show that elevated expression of Kaiso is associated with increased CD47 and SIRPA and decreased THPS1 in ER-negative basal-like tumors." (PMID 37190208, 2023). "To determine the biological significance of Kaiso with the THBS1/CD47/SIRPA signaling axis, we first analyzed two datasets that contained gene expression from commonly utilized breast cancer cell lines." (PMID 37190208, 2023). "To determine the clinical significance of Kaiso with the THBS1/CD47/SIRPA signaling axis in breast cancer patients, we analyzed both the TCGA gene expression and protein dataset." (PMID 37190208, 2023). "One unique approach to fight breast cancer cells is using a CRISPR/Cas9-edited macrophages in which signal-regulatory protein alpha (SIRP-α) is eliminated." (PMID 33926574, 2021). "Recent studies have shown that CD47, the ligand for SIRPα, is a prognostic factor in breast cancer and its expression correlates with SIRPα expression in bone marrow and peripheral blood of breast cancer patients." (PMID 23320069, 2013). "Similarly, IL4IL + phagocytic macrophages in colon and breast cancer showed up-regulated SIRPA expression." (PMID 39696410, 2024). "This SIRPα-induced CD47 signaling in breast carcinoma cells may limit the efficacy of SIRPα decoy therapeutics intended to stimulate innate antitumor immune responses." (PMID 38495618, 2024). "Moreover, blocking CD47-SIRPα interaction with an antibody specific for human SIRPα enhanced killing in vitro by macrophages of HER2+ breast cancer cells previously opsonized with the anti-HER2 monoclonal antibody, trastuzumab." (PMID 31921125, 2019). "Therefore, SIRPα-Fc may be a selective CD47-dependent inducer of stem cell character in these breast carcinoma cells." (PMID 38495618, 2024). "validated the tumor-inhibitory effect of the mouse-derived anti-SIRPα monoclonal antibody MY-1, which showed enhanced cytotoxicity against HER2-positive breast cancer cells in vitro." (PMID 40589735, 2025). "Depleted expression of Kaiso in breast cancer cells modulates the immune signaling molecules within the cargo of exosomes, resulting in increased THBS1 expression and decreased CD47 and SIRPA expression, as well as in decreased phagocytosis by macrophages." (PMID 37190208, 2023). "However, the effects of CC90002 diverged from those of SIRPα-Fc, indicating that effects of therapeutic CD47 binding molecules on breast cancer stem cells are ligand-specific." (PMID 38495618, 2024). "Some studies have demonstrated the concept of delivering Fc-fusion proteins with the help of oncolytic viruses such as SIRPα-Fc fusion protein against ovarian cancer, expression of antibody in HSV-1 oncolytic virus against glioblastoma, and adenovirus against breast cancer in mouse model." (PMID 37146009, 2023). "This approach has been employed to produce exosomes that express SIRPα and blockCD47-SIRPα interactions between tumor cells and T lymphocytes, and to generate exosomes expressing the EGFR-specificpeptide GE11 to promote their interaction with EGFR-positive breast cancer cells." (PMID 32257533, 2020).
breast carcinoma (continued). "However, thus far there are no publications that show a clear correlation between SIRPα expression and outcome, even for breast cancer." (PMID 23320069, 2013).
anemia (28 papers, 2016 to 2025). A reduction in the number of red blood cells, the amount of hemoglobin, and/or the volume of packed red blood cells. "Blocking CD47 or SIRPα promotes macrophage clearance of necHCs and reduces HSC activation (α-SMA, Col1a1); anti-SIRPα avoids anemia associated with CD47 blockade." (PMID 40630093, 2025). "TTI-621 is composed of the N-terminal portion of SIRPα, which demonstrates lower binding affinity to human erythrocytes minimizing the risk of anemia." (PMID 36439116, 2022). "Our data showed that SIRPα-v covered all blood cells and caused anemia as a side effect of the treatment." (PMID 36435797, 2022). "Anti-CD47 mAbs were significantly more likely than selective SIRPα blockers to cause grade 1-2 fever, chills, nausea/vomiting, headache, and anemia." (PMID 36439116, 2022). "SIRPα variants encapsulated by exosomes were less likely to cause anemia and exhibited milder hematotoxicity than naked SIRPα variants and CD47 antibodies." (PMID 36435797, 2022). "This suggests that PD-1/SIRPα nanovesicles may pose a low risk of blood-related side effects, such as anemia." (PMID 39588148, 2024). "CD47–SIRPα-targeting drugs, such as magrolimab and various SIRPα antibodies, have entered multiple clinical trials in oncology; however, known safety risks such as anemia and thrombocytopenia have been identified." (PMID 41479883, 2025). "We previously reported that mice with experimental visceral leishmaniasis (VL) manifest anemia and enhanced hemophagocytosis in the spleen accompanied with decreased SIRPα expression." (PMID 37111479, 2023). "The increase in serum SIRPα levels became evident as early as 12 weeks of infection, which was before the onset of anemia." (PMID 37111479, 2023). "In published trial results, the rates of DLT and grade 1-2 anemia were significantly lower for selective SIRPα blockers." (PMID 36439116, 2022). "Because of the high expression of CD47 in erythrocytes, the major side effect of clinical application of anti-CD47 antibodies and CD47-targeting SIRPα-Fc fusion protein is anemia due to CD47-mediated phagocytosis of erythrocytes." (PMID 36274066, 2022). "This strategy is exemplified by TTI-621, which is a SIRPα-Fc fusion protein engineered for minimal binding to human RBCs, resulting in minimal anemia." (PMID 32038992, 2019). "However, as expected, anti-SIRPα treatment also exacerbated anemia during SAA by 14 dpst, consistent with the role of CD47 as an important “marker of self” on healthy cells, especially red blood cells." (PMID 38724533, 2024). "In clinical trials, anemia is the most common adverse effect of blocking the CD47/SIRPα pathway." (PMID 37138855, 2023). "In summary, Leishmania infection induces both extracellular and intracellular modification of SIRPα in macrophages and may contribute to hemophagocytosis and anemia." (PMID 37111479, 2023). "Moreover, mice devoid of intracellular SIRPα-mediated signaling due to a truncation of the intracellular SIRPα domain (hereafter called “Sirpα mutant mice”) present with mild anemia, splenomegaly due to red pulp expansion and reduced RBC half-life." (PMID 37095207, 2023). "With relatively restricted expression, an SIRPα blockade could enhance the macrophage mediated innate immunity with reduced side effects such as anemia." (PMID 34068552, 2021). "Both routes of administration led to intratumoral infiltration of Sirpα−/− BMDMs, while neither method to infuse Sirpα−/− BMDMs caused adverse reactions such as anemia." (PMID 34050181, 2021). "Lastly, antibodies that target the macrophage ligand SIRPα may also lead to minimal anemia as SIRPα expression is generally restricted to immune effector cells with absent expression on RBCs." (PMID 32038992, 2019). "Therefore, anti-SIRPα is not expected to cause hematologic toxicities such as anemia, thrombocytopenia, and hemagglutination." (PMID 36970051, 2022).
anemia (continued). "Since SIRPα expression is mainly on macrophages and GS‐0189 does not have a functional Fc, it was theorized that GS‐0189 would result in less anemia compared to most CD47‐targeting agents." (PMID 37206279, 2023). "Lack of the intracellular portion of SIRPα can promote accumulation of RBCs at the spleen and the development of anemia in mice, indicating that hemophagocytosis and anemia in VL can be simulated." (PMID 37111479, 2023). "In clinical trials, treatment with TTI‐621 and ALX148 (SIRPα fusion protein) resulted in thrombocytopenia but not anaemia." (PMID 35908284, 2022). "In contrast to CD47 antibodies, the recombinant human (rh)SIRPα‐based therapeutic TTI‐621 did not trigger anaemia in clinical studies." (PMID 35908284, 2022). "Some studies indicate that recombinant SIRPα or anti-CD47 antibodies may lead to anemia but do not specifically attribute intravascular hemolysis to SIRPα antibodies." (PMID 40070841, 2025). "Thus, circumvention of anaemia or thrombocytopenia can be accomplished with various strategies, including the development of CD47 mAbs that bind to a distinct epitope that is not targetable on RBCs or by targeting SIRPα." (PMID 35908284, 2022). "To assess the safety of SIRPα-targeting, we conducted a single-dose toxicity study in cynomolgus monkeys and did not observe obvious signs of toxicity with ADU-1805, in part illustrated by the stable hemoglobin levels in blood, and the lack of acute anemia and thrombocytopenia." (PMID 31801627, 2019).
colorectal cancer (27 papers, 2012 to 2026). A primary or metastatic malignant neoplasm that affects the colon or rectum. "It has been reported that high SIRPA expression is a favorable factor in colorectal cancer, but it is associated with poor prognosis in diffuse large B-cell lymphoma, follicular lymphoma, non-small cell lung cancer, and esophageal carcinoma." (PMID 38920727, 2024). "KWAR23 induced phagocytosis of the DLD‐1 human colorectal cancer cell line across SIRPα variants with equivalent potencies, suggesting that there is no inherent difference in phagocytic capacity of macrophages from patients with different SIRPα variants." (PMID 37206279, 2023). "Through in-depth research on colorectal cancer-associated macrophages, it discovers that Elk-1 expression is positively related to inhibitory receptor signaling regulatory protein-α (Sirpα) expression, which may be intimately connected with the difficulties in curing colorectal cancer malignancies." (PMID 36439106, 2022). "Specifically, AP2α and ELK1 form a regulatory network that facilitates the SIRPα expression in tumor-associated macrophages, which was associated with poor survival in colorectal cancer, suggesting that AP2α and ELK1 could promote the transcription of both H2A.Z isoforms." (PMID 35317119, 2021). "In colorectal cancer, SIRPα-expressing TAMs suppress antitumor responses independently of CD47, whereas SIRPα-deficient macrophages enhance CD8+ T cell activation, particularly when combined with radiotherapy." (PMID 41486149, 2026). "For example, radiotherapy upregulates CD47 on tumor cells and SIRPα expression on myeloid cells in colorectal cancer." (PMID 40835598, 2025). "The role of SIRPα/CD47 blockade in the treatment of MSS colorectal cancer needs to be further elucidated in future trials." (PMID 41171165, 2025). "For example, the application of anti-SIRPα and anti-PD-1 combined with radiotherapy activates more robust adaptive antitumor immune responses in colorectal cancer." (PMID 40835598, 2025). "Surprisingly, some solid cancers (such as renal cell carcinoma, colorectal cancer, and osteosarcoma) exhibit high levels of SIRPα expression." (PMID 40589735, 2025). "Combined therapy with radiotherapy/anti-SIRPα/anti-PD-1 for colorectal cancer was shown to effectively induce cGAS–STING signaling in DCs both in vitro and in vivo, facilitating efficient cross-presentation of tumor-associated antigens." (PMID 40589735, 2025). "Our study revealed a positive correlation between SIRPα expression at the tumor site and PD-L1 in colorectal cancer patients, suggesting the rationale for simultaneously targeting SIRPα and PD-L1 in colorectal cancer treatment." (PMID 38462636, 2024). "The combination of OH2 and anti-SIRPα antibodies had a significant effect on the treatment of the mouse colorectal cancer CT-26 model." (PMID 36310169, 2022). "Here, we found that the expression of Sirpα in TAMs increased dynamically with colorectal cancer (CRC) progression." (PMID 32296015, 2020). "A plausible explanation for these opposing findings is that the M1/M2 TAM ratio and/or the tumor-phagocytotic capacity of TAMs in colorectal cancer would likely be higher than those of the second group of tumors where high SIRPA expression correlates with poor outcome." (PMID 38920727, 2024). "Activation of XBP1 in TAMs promotes the progression of colorectal cancer, which may be related to the upregulation of SIRPα and THBS1, and the inhibition of macrophage phagocytosis." (PMID 37954130, 2023). "Our SIRPα mAbs competed with CD47 for binding to human SIRPα and exhibited a potent phagocytic effect when combined with the anti-EGFR antibody on colorectal cancer cell lines." (PMID 40136470, 2025). "The signal regulatory protein α (SIRPα)/CD47 axis is an inhibitory phagocytosis immune checkpoint expressed on phagocytes and colorectal cancer cells, respectively, blocking phagocytosis of tumor cells." (PMID 41171165, 2025).
colorectal cancer (continued). "Protein levels of SIRPα and CD163 were additionally confirmed by IHC in tumor samples from patients with colorectal cancer, SCCHN, and DLBCL." (PMID 38319147, 2024). "EVs derived from HEK293T cells were engineered with SIRPα on their surface (EV-SIRPα), in order to target and block CD47 in a colorectal cancer model." (PMID 31963216, 2020). "Moreover, diHEP-DPA blocked immunosuppression by reducing the expression of SIRPα in TAMs and CD47 in colorectal cancer cells." (PMID 34573091, 2021).
glioblastoma (25 papers, 2015 to 2026). The most malignant astrocytic tumor (WHO grade IV). "Immunofluorescence staining was applied to compare difference in SIRPA expression between tumor and peritumoral tissues, and spatial association of SIRPA+ macrophages with glioblastoma stem cells (GSCs) was investigated." (PMID 42116089, 2026). "The usage of a soluble recombinant fusion protein encoding the N-terminal CD47 binding domain of human SIRPα was proven effective as anti-tumor therapy for selected hematopoietic malignancies and several solid tumors, including glioblastoma." (PMID 35054787, 2022). "An original representative image of the multiplex imaging of glioblastoma resected as a lobectomy in continuity with the adjacent infiltrating brain shows that SIRPα expression is particularly prominent at the leading-edge/infiltrating region." (PMID 38786045, 2024). "For example, since the CD47/SIRPα axis resides at the infiltrating margin of glioblastoma, including the adjacent microglia population, these regions typically have an intact BBB." (PMID 38786045, 2024). "Recently, murine-specific SIRPα Nbs were successfully employed for non-invasive single-photon emission tomography imaging of myeloid cells in intracranial glioblastoma tumors of experimental mice." (PMID 38164132, 2023). "To show the versatility of our gene-editing platform, we edited the CD14, CD47, TREM2, SIRPA and MERTK genes implicated in the clearance of Aβ and glioblastoma cells." (PMID 37483607, 2023). "We further determined the potential mechanism by which increased SIRPα expression in macrophages for glioblastoma progression in our study." (PMID 35410993, 2022). "By inhibiting HA synthesis in glioblastoma cells with 4MU, we found that the expression level of CD47 was decreased in glioblastoma cells and that SIRPα expression was increased in macrophages." (PMID 35410993, 2022). "In addition, other tumor indications, such as renal cell carcinoma, glioblastoma, metastatic melanoma, and mesothelioma, displayed high expression of both SIRPα and macrophage genes." (PMID 38319147, 2024). "When the spatial distribution of CD47 and SIRPα mRNA is assessed within glioblastoma, both CD47 and SIRPα are expressed to a greater extent at the leading edge, indicating this may be a mechanism for immune evasion as tumor cells infiltrate the brain." (PMID 38786045, 2024). "Collectively, these findings indicated that HA plays a crucial role in macrophages polarization and CD47/SIRPα signaling between glioblastoma cells and macrophages, and suppressing the HA pathway may be a new immunotherapeutic approach for glioblastoma." (PMID 35410993, 2022). "This phenomenon could be explained as follows: to protect glioblastoma cells from phagocytosis by macrophages, the reduced expression of CD47 on the glioblastoma cell surface can lead to increased expression of SIRPα in macrophages via a feedback mechanism." (PMID 35410993, 2022). "To evaluate the expression and distribution of SIRPα within the glioblastoma (GBM) microenvironment, we reanalyzed our recently published single-cell RNA sequencing (scRNA-seq) and cellular indexing of transcriptomes and epitopes sequencing (CITE-seq) datasets of human and mouse GBM." (PMID 34917090, 2021). "Similarly, CD172a (SIRPA) was found on the majority of cellular species but was most highly expressed on glioblastoma cells, reflecting published data that showed high expression of CD172a in brain." (PMID 25894527, 2015). "For example, 99mTc-labeled VHHs could successfully target SIRPα in glioblastoma." (PMID 37746282, 2023). "Interestingly, inhibition of glioblastoma HA synthesis with 4-methylumbelliferone (4MU) also led to downregulation of CD47 expression in glioblastoma cells and upregulated SIRPα expression in macrophages, which further facilitated the phagocytosis of glioblastoma cells by macrophages." (PMID 35410993, 2022).